PCGF2 (polycomb group ring finger 2)
Description:
Transcriptional repressor. Binds specifically to the DNA sequence 5'-GACTNGACT-3'. Has tumor suppressor activity. May play a role in control of cell proliferation and/or neural cell development. Regulates proliferation of early T progenitor cells by maintaining expression of HES1. Also plays a role in antero-posterior specification of the axial skeleton and negative regulation of the self-renewal activity of hematopoietic stem cells (By similarity). Component of a Polycomb group (PcG) multiprotein PRC1-like complex, a complex class required to maintain the transcriptionally repressive state of many genes, including Hox genes, throughout development. PcG PRC1 complex acts via chromatin remodeling and modification of histones; it mediates monoubiquitination of histone H2A 'Lys-119', rendering chromatin heritably changed in its expressibility. Within the PRC1-like complex, regulates RNF2 ubiquitin ligase activity.
Synonyms: RNF110; ZNF144; MEL-18; TPFS
Tractability: PROTAC: UniProt records ubiquitination sites on it; ubiquitination databases record sites on it; its protein half-life has been measured.
Gene: Protein-coding gene on chromosome 17 (38,733,894 to 38,752,555, reverse strand). Ensembl gene ENSG00000277258.
Subcellular location: Nucleus
Subcellular location (Human Protein Atlas): Nucleoplasm
Pathways (Reactome):
Metabolism of proteins: SUMOylation of DNA damage response and repair proteins; SUMOylation of DNA methylation proteins; SUMOylation of RNA binding proteins; SUMOylation of chromatin organization proteins; SUMOylation of transcription cofactors
Developmental Biology: Activation of anterior HOX genes in hindbrain development during early embryogenesis
Gene expression (Transcription): Transcriptional Regulation by E2F6
Gene Ontology:
Molecular function: protein binding; promoter-specific chromatin binding
Biological process: chromatin remodeling; negative regulation of transcription by RNA polymerase II; heterochromatin formation; negative regulation of DNA-templated transcription; chromatin organization
Cellular component: chromatin; nucleoplasm; nucleus; PcG protein complex; PRC1 complex
Genetic constraint (gnomAD): Loss-of-function variants: 8 observed, 32.6 expected, observed/expected ratio (o/e) 0.25, 90% interval 0.14 to 0.44. The upper end of that interval is the gene's LOEUF score, 0.44, which puts it in group 1 of 6, group 1 being the genes least tolerant of losing a copy. Missense variants: 424 observed, 417.91 expected, observed/expected ratio (o/e) 1.01, 90% interval 0.94 to 1.1. Synonymous variants: 196 observed, 169.65 expected, observed/expected ratio (o/e) 1.16, 90% interval 1.03 to 1.3.
Gene-disease validity (ClinGen):
ClinGen rates the evidence that PCGF2 causes each of these diseases.
turnpenny-fry syndrome (autosomal dominant): Strong.
Homologues: Orthologues: chimpanzee PCGF2 (99% identical), macaque PCGF2 (99% identical), pig PCGF2 (97% identical), dog PCGF2 (97% identical), mouse Pcgf2 (95% identical), rat Pcgf2 (95% identical), guinea pig PCGF2 (94% identical), rabbit PCGF2 (88% identical), tropical clawed frog pcgf2 (64% identical), Drosophila melanogaster Su(z)2 (33% identical), Drosophila melanogaster Psc (17% identical). Paralogues in human: BMI1 (62% identical), PCGF1 (25% identical), PCGF3 (24% identical), PCGF6 (24% identical), PCGF5 (23% identical), RING1 (17% identical), RNF2 (16% identical).
Diseases named in the same sentence as PCGF2 in open-access papers:
PCGF2 is named in the same sentence as 34 diseases in open-access papers, as found by Europe PMC text mining. Sharing a sentence is not in itself a finding about the gene and the disease. The quoted sentences say what the papers report.
breast carcinoma (14 papers, 2010 to 2025). "AKT phosphorylates PCGF2 to disrupt the interaction between PCGF2 and other PRC1 members that cause tumorigenesis in breast cancer." (PMID 39337298, 2024). "In contrast, some subunits of PRC1 have also been reported to have tumor-suppressive roles such as CBX6 and PCGF2 in breast cancer." (PMID 36076977, 2022). "We also noticed that other amplified cPRC1 genes, including CBX2/4/8 and PCGF2, exhibited distinct expression patterns when categorized by breast cancer subtype." (PMID 30139998, 2018). "PCGF2 serves as a tumor suppressor in breast cancer, gastric cancer, and colon cancer probably for the negative regulation of Akt activation." (PMID 35832194, 2022). "For example, PHF20L1, BCAS3, TAOK1, PCGF2, and TRPS1 are fused in other breast cancers." (PMID 23260012, 2012). "However, RNF2, PCGF2, and CBX2/4/8 expression was higher in all four breast cancer stages compared to normal breast tissue, suggesting that their overexpression was not predictive of breast cancer aggressiveness." (PMID 30139998, 2018).
gastric cancer (7 papers, 2010 to 2023). A primary or metastatic malignant neoplasm involving the stomach. "PCGF2 serves as a tumor suppressor in BC, gastric cancer, and colon cancer, probably for the negative regulation of Akt activation." (PMID 37715225, 2023).
developmental delay (3 papers, 2022 to 2023). "PCGF2 is associated with phenotypes such as intellectual disability, global developmental delay, and mental retardation in the OpenTargets database." (PMID 36414996, 2022).
epilepsy (2 papers, 2023 to 2025). A brain disorder characterized by episodes of abnormally increased neuronal discharge resulting in transient episodes of sensory or motor neurological dysfunction, or psychic dysfunction. "TPFS, resulting from a heterozygous mutation in the PCGF2 gene on chromosome 17q12, is associated with a spectrum of developmental abnormalities; however, epilepsy has not been well documented as a feature of this condition." (PMID 40502890, 2025).
Intellectual disability (2 papers, 2022). "To date, 13 cases with pathogenic variants in the PCGF2 gene have been described, with prevalent features including intellectual disability, impaired growth (including intrauterine), and a range of cardiovascular and skeletal anomalies." (PMID 35281813, 2022).
anovulation (1 paper, 2022). The absence of ovulation. "Our study highlights that the mutation of Pcgf2 may be a pathogenic factor of secondary premature ovarian insufficiency (POI) and anovulation." (PMID 36407101, 2022).
glioma (1 paper, 2022). A benign or malignant brain and spinal cord tumor that arises from glial cells (astrocytes, oligodendrocytes, ependymal cells). "Although having not been reported in glioma-related research, TRIM34, PCGF2, TLE3, and TRIM17 have been revealed to contribute to the carcinogenesis of other cancers." (PMID 35832194, 2022).
immune deficiency (1 paper, 2024). "Mouse embryos deficient in PCGF2 and PCGF4/BMI1 exhibit similar posterior transformations of the axial skeleton and display severe immune deficiency." (PMID 39337298, 2024).
turnpenny-fry syndrome (1 paper, 2025). "Turnpenny-Fry syndrome (TPFS) is caused by a heterozygous mutation in the PCGF2 gene on chromosome 17q12." (PMID 40502890, 2025).
tumor (26 papers, 2007 to 2025). "It is caused by mutations in the Polycomb Group Ring Finger Protein 2 (PCGF2) gene, which is also known to play a role in numerous tumor types." (PMID 38283775, 2024). "We speculate that PCGF2 may play a tumor suppressing role or act as an oncogene by affecting the ubiquitination levels of different substrate proteins." (PMID 36123926, 2022). "Additionally, CHD3 levels negatively correlated with tumor grade, and PCGF2 and PCGF3 levels positively correlated with ER+ status." (PMID 27863398, 2016). "PCGF2 is a polycomb protein that could act as a tumor suppressor." (PMID 20932292, 2010). "PCGF2 is also a component of the PRC1 core complex and maintains the transcriptional repression of genes involved in embryogenesis, cell cycle, and tumor suppression." (PMID 35179962, 2022). "Among the most downregulated proteins, we found several confirmed or candidate tumour suppressor genes (eg, ID1, FAS, FPR1, IL10, PCGF2, VDR)." (PMID 25594007, 2014). "On the other hand, we found FAS, FPR1, ID1, IL10, PCGF2, VDR among downregulated proteins: all are involved in tumor immune-escape through induction of apoptosis and anti-inflammatory activities." (PMID 25594007, 2014). "Nevertheless, PCGF2 and PSMB3 are rarely amplified with ERBB2 in tumors, and PCGF2 has been reported to be a tumor suppressor." (PMID 17584934, 2007). "Most notably, unlike other PCGF homologs, PCGF2 (also known as MEL-18) has tumor-suppressive activity." (PMID 36076977, 2022). "In these ceRNA triplets, miR-484, miR-181a-5p, miR-423-5p and let-7b-5p were identified as miRNA biomarkers with excellent distinguishing ability between normal and tumor tissues, and ANKRD36, PCGF2, EZH2 and ATP6V1F were closely related to the prognosis of corresponding cancer." (PMID 33194594, 2020).
cancer (17 papers, 2007 to 2023). A tumor composed of atypical neoplastic, often pleomorphic cells that invade other tissues. "We found that the perturbation scores of modules relating to mitosis, extracellular matrix, and RNA metabolism as well as transcriptional targets of polycomb group ring finger proteins BMI1 and PCGF2 were recurrently associated with disease progression in 3 or more cancers." (PMID 36950380, 2023). "For instance, we identified phase shifted transcript pairs from different cancer hallmark genes such as BIRC5 in HCT116_WT, PCGF2 in HCT116_ARNTLKO, ABCA2 in HCT116_NR1D1KO, and CHD8 in HCT116_PER2KO." (PMID 35552415, 2022). "Recent studies have revealed that the PCGF family of proteins (PCGF1 (Nspc1), PCGF2 (Mel-18), PCGF3, PCGF4 (Bmi1), PCGF5 and PCGF6 is robustly elevated in diverse human cancers and promotes cancer progression." (PMID 34148069, 2021). "Similarly, in 1M-84, DHFR* is integrated between PCGF2 (Mel-18) and PSMB3, approximately 1 Mb proximal to ERBB2, a gene frequently amplified in cancer." (PMID 17584934, 2007).
neurodegenerative disease (1 paper, 2022). A disorder of the central nervous system characterized by gradual and progressive loss of neural tissue and neurologic function. "Specific TFs activated with an NES > 0 (female PD patients), such as ATF3, BCL6, or PCGF2, have been associated with neurodegenerative diseases or cognitive disabilities." (PMID 36414996, 2022). "Of the transcription factors altered in female PD patients, ATF3, BCL6, and PCGF2 have been previously associated with neurodegenerative diseases or cognitive disabilities." (PMID 36414996, 2022).
neurodevelopmental disorder (1 paper, 2022). A behavioral and cognitive disorder with onset during the developmental period that involves impaired or aberrant development of intellectual, motor, or social functions. "Mutations in PRC1 members such as PHC1 and PCGF2 lead to human neurodevelopmental disorders." (PMID 36117635, 2022).
PCGF2 also shares sentences with these, for which no sentence is quoted: colon cancer (4 papers); melanoma (3); prostate carcinoma (3); gastric tumor (2); lymph node metastasis (2); rectal cancer (2); ameloblastoma (1); breast tumors (1); cardiac hypertrophy (1); Expressive language delay (1); Fibroadenoma (1); growth retardation (1); heart failure (1); Hypertension (1); Infertility (1); leukemia (1); medulloblastoma (1); odontogenic keratocysts (1); ovarian carcinoma (1); sarcopenia (1); tuberculosis (1).